VIM (vimentin)
Diseases named in the same sentence as VIM in open-access papers (continued):
Sharing a sentence is not in itself a finding about the gene and the disease.
rheumatoid arthritis (68 papers, 2006 to 2025). A chronic, systemic autoimmune disorder characterized by inflammation in the synovial membranes and articular surfaces. "Citrullination of vimentin intermediate filaments leads to secretion of citrullinated vimentin (Cit-Vim) as an autoantigen implicated in the pathogenesis of rheumatoid arthritis (RA)." (PMID 35573702, 2022). "Concerning VIM protein, it has been linked with several pathophysiological conditions such as cancer, rheumatoid arthritis, and HIV." (PMID 33117167, 2020). "Specific mutations in vimentin are correlated with diseases such as cataracts, Crohn’s disease, rheumatoid arthritis, and human immunodeficiency virus." (PMID 30248895, 2018). "Vimentin is a protein that has been linked to a large variety of pathophysiological conditions, including cataracts, Crohn’s disease, rheumatoid arthritis, HIV and cancer." (PMID 30248895, 2018). "Antibodies against mutated citrullinated vimentin (AMCV) represent a useful diagnostic marker with correlation to disease activity in patients with rheumatoid arthritis (RA)." (PMID 26268352, 2015). "Antibodies against citrullinated proteins/peptides (ACPAs), and especially antibodies targeting mutated citrullinated vimentin (anti-MCVs), are novel biomarkers of rheumatoid arthritis (RA)." (PMID 23573111, 2013). "Autoantibodies against mutated and citrullinated vimentin (MCV) represent a novel diagnostic marker for rheumatoid arthritis (RA)." (PMID 20569500, 2010). "Recently, we identified a novel antigenic isoform of vimentin in patients with rheumatoid arthritis, which was modified by citrullination and mutation (MCV)." (PMID 20569500, 2010). "Notably, citrullinated vimentin is one of the most highly cited candidate antigens linked to rheumatoid arthritis that trigger autoimmune reactions." (PMID 40251523, 2025). "Vimentin is a citrullinated antigen in rheumatoid arthritis, which may underlie pathogenesis and be externalized during NETosis." (PMID 37534129, 2023). "In addition to its role in CD and host response to infection, vimentin has been linked with a growing number of diseases, including cancers, cataracts, rheumatoid arthritis and atherosclerosis." (PMID 30699149, 2019). "Furthermore, the interest of antibodies to mutated citrullinated vimentin for diagnosing rheumatoid arthritis in anti-CCP-negative patients and for monitoring infliximab therapy was recently suggested." (PMID 19284558, 2009). "Notably, modified antibodies associated with rheumatoid arthritis, in which citrulline has replaced arginine, recognize a variety of proteins that were also identified after nerve injury such as collagen, fibronectin, histones and vimentin." (PMID 40196481, 2025). "Nonetheless, in the context of inflamed tissues, such as the synovium of rheumatoid arthritis, PADs are activated through an influx of Ca2+, which then leads to vimentin citrullination." (PMID 40251523, 2025). "Of note, elevated levels of citrullinated proteins, such as histones and vimentin, have been linked to rheumatoid arthritis (RA), suggesting that citrullination may contribute to the pathological implications of RA and cancer." (PMID 40751052, 2025). ": ECV or vimentin antibodies are often used as markers of pathology, such as in rheumatoid arthritis." (PMID 40251523, 2025). "Citrullinated vimentin (CV) is a modified protein found only in rheumatoid arthritis, and CV⁃CAR⁃Treg can specifically recognize CV or CV+ cells in patients with RA, thus improving the specific localization of Treg." (PMID 40103816, 2025). "Enhanced NETosis, which is characterized by the extrusion of citrullinated vimentin, also contributes to the aberrant adaptive and innate immune responses observed in the pathogenesis of rheumatoid arthritis." (PMID 40251523, 2025). "For example, citrullinated proteins such as histones and vimentin serve as neoepitopes for anti-citrullinated protein antibodies (ACPA) in rheumatoid arthritis (RA)." (PMID 40342425, 2025).
rheumatoid arthritis (continued). "Sonoma Biotechnologies’s pipeline includes SBT-77-7101, a CAR-Treg product specific to citrullinated vimentin (CV), a known antigen present in the synovial fluid (SF) of Rheumatoid arthritis (RA) patients." (PMID 38283365, 2023). "This was demonstrated using CAR Tregs specific for citrullinated vimentin (CV), a protein abundantly and almost exclusively found in the inflamed joint extracellular matrix in rheumatoid arthritis (RA) patients." (PMID 36562079, 2023). "These included anti-complement 3 (lupus), anti-complement C1q (lupus), anti-SP100 (lupus), PR-3 (vasculitis), anti-LC-1 (autoimmune hepatitis), anti-Nup62 (primary biliary cirrhosis), anti-MI-2 (myositis), and anti-vimentin (rheumatoid arthritis)." (PMID 33897700, 2021). "This is an enzymatic modification catalyzed by peptidyl arginine deiminases that turns vimentin into an antigen in rheumatoid arthritis, but also into an antigen for anti-tumor immunity." (PMID 32630064, 2020). "For example, the citrullinated form of vimentin is expressed in patients with rheumatoid arthritis, as indicated further below (3.11)." (PMID 30248895, 2018). "Intriguingly, a citrullinated form of vimentin is known to be elicit an immune response in rheumatoid arthritis, which correlated with disease activity." (PMID 28114394, 2017). "The vimentin sequence of TVETrDGQVINETSQHHDDLE identified here in blast injury precisely matches the site (indicated by “r”) found to be deiminated in rheumatoid arthritis." (PMID 28626499, 2017). "Acetylated Vimentin appears to be clinically relevant though, in that acetylated Vimentin antibodies have been found in the sera of patients with rheumatoid arthritis." (PMID 26999212, 2016). "In this study, autoantibodies against mutated and citrullinated vimentin (MCV), considered as diagnostic marker for rheumatoid arthritis, are measured in serum samples and in whole blood." (PMID 25047039, 2014). "We evaluated the association between anti-cyclic citrullinated peptide antibodies (anti-CCP) and anti-mutated citrullinated vimentin antibodies (anti-MCV) with the presence of extra-articular (ExRA) manifestations in 225 patients with rheumatoid arthritis (RA)." (PMID 24804270, 2014). "Vimentin expression seems to be increased in inflammatory and immunological processes evident in studies involving patients with rheumatoid arthritis and Group A streptococcal infections." (PMID 23382852, 2013). "Antibodies to vimentin have been observed in several different autoimmune conditions including rheumatoid arthritis and systemic lupus erythematosus and also following solid-organ transplantation." (PMID 22022619, 2011). "In rheumatoid arthritis, modified citrullinated vimentin isoforms are generated and act as autoantigens." (PMID 20169076, 2010). "During apoptosis, vimentin can be exposed on the cell surface and triggers the generation of autoantibodies in some patients with rheumatoid arthritis." (PMID 21209908, 2010). "Increased expression of eVim and its post-translationally modified (PTM) form, citrullinated vimentin (CitVim), has been observed in various acute inflammatory conditions such as sepsis and chronic conditions like pulmonary fibrosis or rheumatoid arthritis (RA)." (PMID 39910535, 2025). "Extracellular vimentin is expressed in several pathophysiological conditions, and several reports indicate its role in mediating response to cellular damage or as an autoantigen in rheumatoid arthritis." (PMID 37356720, 2023). "It is also noteworthy that citrullinated vimentin peptides with the same sequence as the citrullinated vimentin peptides found in pediatric brain tumor tissues have been described for their immunoregulatory and anti-inflammatory properties in rheumatoid arthritis." (PMID 37761239, 2023).
rheumatoid arthritis (continued). "However, in autoimmune diseases such as rheumatoid arthritis, it is known that overactivation of PADIs can lead to citrullination of specific proteins like fibrinogen and vimentin, triggering an immune response that contributes to the disease." (PMID 37648716, 2023). "Here, we also treated cells with citrullinated vimentin, which is the form of vimentin that is secreted in patients suffering from rheumatoid arthritis, to see whether the effects seen here are different to those of recombinant vimentin." (PMID 34299089, 2021). "Additionally, extracellular vimentin can exist in different isoforms such as oxidized vimentin, citrullinated vimentin, and carbamylated vimentin which undergo post-translational modifications under certain circumstances (senescence, rheumatoid arthritis)." (PMID 34299089, 2021). "Nevertheless, the exact mechanism of the vimentin triggered immune response in rheumatoid arthritis is unknown." (PMID 28114394, 2017). "Hence assaying antibodies to citrullinated -vimentin is a more sensitive assay for measuring disease severity of rheumatoid arthritis than assaying antibodies to native vimentin." (PMID 23777935, 2013). "In addition to their physiological roles, vimentin and calreticulin are targets in autoimmune conditions, like rheumatoid arthritis." (PMID 21209908, 2010). "The autoantibodies associated with rheumatoid arthritis (RA) predominantly consist of RF, ACPA, anti-modified citrullinated vimentin antibody, anti-carbamylated protein antibody, anti-PAD-4 antibody, and anti-GPI antibody." (PMID 39049070, 2024). "Citrullinated vimentin and citrullinated fibrinogen are major autoantigens in rheumatoid arthritis (RA)." (PMID 35885618, 2022). "Particularly, rheumatoid arthritis (RA) patients produce antibodies against citrullinated proteins, including vimentin, that can be used for diagnosis." (PMID 32630064, 2020). "In a comparison of biopsies from normal and rheumatoid arthritis diseased tissues, the healthy tissues expressed epithelial-like biomarkers (e.g., E-cadherin, collagen type IV), while the pathological synovium expressed fibrotic markers (e.g., α-smooth muscle actin, vimentin)." (PMID 30248895, 2018). "Citrullination has also been regarded as a possible mechanism of breaching immunological tolerance, leading to rheumatoid arthritis (RA), as PPAD can modify several human proteins, such as fibrinogen, α-enolase, vimentin and histones." (PMID 38576615, 2024). "The deimination sites found within vimentin and GFAP corresponded to previously reported sites of deimination, respectively, in rheumatoid arthritis and in multiple sclerosis and Alzheimer's disease." (PMID 28626499, 2017). "In later reports, peptides from myelin basic protein (MBP) and other autoantigens were identified in central nervous system (CNS) samples from multiple sclerosis (MS) patients, and peptides from collagen, vimentin, and others were detected in synovial samples from rheumatoid arthritis (RA) patients." (PMID 24381570, 2013). "Autoantibodies to vimentin (AVA) are commonly produced by patients with autoimmune diseases such as Lupus and rheumatoid arthritis, they are also found after solid organ transplantation." (PMID 23777935, 2013). "Antibodies directed against citrullinated vimentin are members of the family of autoantibodies reactive with citrullinated proteins and are among the most specific serological markers for the diagnosis of rheumatoid arthritis (RA)." (PMID 16859519, 2006). "Therefore, it is conceivable that the patient developed seropositive rheumatoid arthritis as a result of CHIKV infection, particularly given that the citrullinated vimentin antibody (anti-Sa) was positive in this patient." (PMID 40042325, 2025). "This is important to the present study and in periodontitis without rheumatoid arthritis, although the level of vimentin is elevated in gingival crevice fluid." (PMID 37190018, 2023).
rheumatoid arthritis (continued). "For instance, rheumatoid arthritis (RA) patients exhibit memory CD4+ T cells specific for various citrullinated antigens, including citrullinated aggrecan and citrullinated vimentin, which correspond to autoantibodies directed against citrullinated antigens and proteins in these patients." (PMID 32106536, 2020). "It would be intriguing to replicate our experiments and stimulate PBMCs from patients with rheumatoid arthritis and other autoimmune connective tissue disorders (such as SLE or Sjogren’s syndrome) with both vimentin and Kv in an attempt to elict a similar pro-inflammatory cytokine secretion." (PMID 28114394, 2017). "But rheumatoid arthritis (RA)–related antibodies including rheumatoid factor (RF), anti–cyclic citrullinated peptide (a-CCP), antikeratin antibody, anti–perinuclear factor, and anti–mutated citrullinated vimentin were all negative." (PMID 38125646, 2023). "Citrullinated vimentin was found with increased abundance in the colonic tissue of these patients compared to the controls, which could indicate that initial rheumatoid arthritis triggering is not limited just to a specific location in the body but can take place in many other locations." (PMID 28948174, 2017). "Additionally, the epithelial and glandular components of salivary glands express vimentin, enolase, and other proteins that are potential substrates for PAD2, and some of these proteins have been recognised as autoantigens in autoimmune diseases, including rheumatoid arthritis." (PMID 23533719, 2013).
viral infection (68 papers, 2007 to 2026). "Viral infection causes vimentin filament disassembly into soluble oligomers with hydrophobic and acidic interfaces conducive to viral binding." (PMID 41516263, 2025). "Three host proteins associated with viral infections, vimentin (VIM), tripartite motif-containing protein 21 (TRIM21), and Tu translation elongation factor (TUFM) interacted with D1133L in vitro." (PMID 36406406, 2022). "This proposal indicates the pluripotential hallmark of vimentin during viral infection, which needs to be investigated in the future." (PMID 34372621, 2021). "As many virus infections are accompanied by a rearrangement and even a loss of cellular filaments, especially vimentin and actin, we have investigated potential changes in vimentin intermediate filaments and actin filaments during EV71 infection." (PMID 24073199, 2013). "The vimentin-formed IFs (VIFs) have been linked to multiple stages of virus infection." (PMID 36851648, 2023). "In addition to virus-host interactions and viral life cycle, Vimentin intermediate filaments are associated with the pathogenesis of viral infections mediated ALI." (PMID 35573702, 2022). "The need for therapeutic tools in the fight against SARS-CoV-2, the virus causing the COVID-19 pandemic, has fostered the interest in vimentin as a potential therapeutic target in viral infections, a subject addressed in several recent reviews and hypotheses." (PMID 35487944, 2022). "Moreover, three randomly selected proteins associated with viral infections: VIM, TRIM21, and TUFM were confirmed to interact with D1133L by co-IP and IFA assays." (PMID 36406406, 2022). "Moreover, VP1 caused the vimentin rearrangement in astrocyte cells, facilitating virus infection in the CNS." (PMID 31512144, 2020). "The purpose of this review is to investigate the abundant evidence on vimentin involvement in infection and associated damage and hypothesize about its potential interest as an additional therapeutic target against certain viral infections." (PMID 32630064, 2020). "Although vimentin knockout mice provide a vimentin-deficient background, genetic knockout may induce compensatory developmental or physiological changes that could influence viral infection pathways or immune responses." (PMID 41516263, 2025). "Therefore, changes in tissue and extracellular vimentin expression and associated signal trails may determine/protect the fate of cells and the progression of disease caused by viral infection." (PMID 34372621, 2021). "In addition to virus infections, vimentin is associated with several significant human diseases." (PMID 31619557, 2020). "Further mechanistic studies revealed that MEK1/2 inhibitors prevent viral infection by promoting the dispersion of intracellular vimentin network, thereby disrupting the cytoskeletal structure required for viral replication." (PMID 41137718, 2026). "Our findings highlight the pro-viral “shield” and anti-viral “sabotage” role, a context-dependent role of vimentin during viral infection." (PMID 41516263, 2025). "Vimentin serves as a critical accomplice in viral infection, being exploited by viruses to facilitate their own replication, dissemination, and evasion of immune clearance." (PMID 41148832, 2025). "In particular, the presence of vimentin outside of a cell contributes to the pathogenesis of infectious diseases by modulating the initial steps of viral infection." (PMID 40733526, 2025). "Here, this review summarizes the pro-viral “shield” and anti-viral “sabotage” roles of dynamic vimentin during viral infection, influencing viral entry and replication." (PMID 41516263, 2025). "Both cytoskeleton components are involved in cell fusion, hence why the results from qRT-PCR demonstrated that the viral infection induced a decrease in vimentin mRNA expression versus mock-infected MSC-PL." (PMID 40573358, 2025). "Accordingly, it has been assessed that vimentin expression rapidly increased in case of viral infection." (PMID 38535592, 2024).